SLC7A11 (solute carrier family 7 member 11)
Diseases named in the same sentence as SLC7A11 in open-access papers (continued):
Sharing a sentence is not in itself a finding about the gene and the disease.
cancer (continued). "Further exploration and validation of disulfidptosis-targeting strategies in preclinical and clinical settings could usher in a new era of precision medicine for SLC7A11-high cancers." (PMID 38428031, 2024). "The overexpression of GPX4 is found in cancers with poor prognosis together with SLC7A11." (PMID 38674143, 2024). "Further progress in the understanding of how epigenetic mechanisms influence SLC7A11 expression may potentially identify novel therapeutic targets for cancer cells that are resistant to ferroptosis." (PMID 39624080, 2024). "Several cancer cells rely on SLC7A11 to import cystine to maintain redox balance and cell survival." (PMID 38799433, 2024). "The research team discovered in their 2020 study that certain cancer cells may be sensitive to glucose transporter inhibitors due to their high expression of SLC7A11 and the resultant “addiction” to extracellular glucose." (PMID 38334964, 2024). "In cancer tissues, the expression of SLC7A11 tended to be higher." (PMID 38191330, 2024). "On the other hand, cancer cells mainly acquire cysteine from outside their environment via SLC7A11." (PMID 38994627, 2024). "SLC7A11, the catalytic subunit of system xc−, functions as a transporter responsible for cysteine influx into cells, a process pivotal for the survival and growth of cancer cells." (PMID 39090114, 2024). "In fact, SLC7A11 is often upregulated in cancer cells while they adapt to oxidative stress." (PMID 38739940, 2024). "Cancer cells require a large amount of cysteine and glutathione to neutralize the high levels of reactive oxygen species in their cells, resulting in an upregulation of SLC7A11 as a component of their reliance on nutrients." (PMID 39807126, 2024). "The cystine/glutamate antiporter SLC7A11 plays a key effect in the introduction of cystine into the synthesis of glutathione and antioxidant defense and is highly expressed in numerous human cancers." (PMID 38385087, 2024). "Furthermore, the authors have found that SOX2 increases SLC7A11 to protect cancer cells from ferroptosis, and mutations in SOX2 binding sites in SLC7A11 gene sensitize cancer cells to ferroptosis." (PMID 38705513, 2024). "SLC7A11 (also known as xCT) is overexpressed in multiple cancers, including TNBC." (PMID 38675657, 2024). "Therefore, the increased expression of SLC7A11/xCT on cancer cell surfaces enhances the uptake of cystine for intracellular GSH synthesis." (PMID 38790657, 2024). "Additionally, the targeted treatment strategy of SLC7A11 in cancer therapy has demonstrated its potential in the management of specific malignant tumors." (PMID 39807126, 2024). "Hence, our findings demonstrate that SFN exerts its anti-cancer effects through inducing SLC7A11-dependent ferroptosis in OS, providing compelling evidence for the application of SFN in OS treatment." (PMID 39657365, 2024). "However, an exception observed is that SLC7A11 methylation levels tended to correlate with worse cancer patient survival, especially in LIHC." (PMID 38397869, 2024). "For instance, certain immune cells such as CD8+ T cells might trigger ferroptosis in cancer cells by reducing the production of SLC7A11." (PMID 39769017, 2024). "Consequently, the POU2F2/PTPRG-AS1/miR-376c-3p/SLC7A11 axis holds potential as both a novel biomarker and therapeutic target for ferroptosis-mediated cancer therapy in TNBC." (PMID 39867656, 2024). "By targeting SLC7A11 and its associated pathways, novel therapeutic strategies can be developed to disrupt the metabolic vulnerabilities of cancer cells, potentially leading to more effective treatments for LUAD and other cancers." (PMID 38655266, 2024). "Notably, to ensure the increased glutaminolysis, cancer cells secrete partial glutamate, in exchange of extracellular cystine, through its transporters, Xc− system, consisting of SLC7A11 and SLC3A2." (PMID 40440083, 2024).
cancer (continued). "Interestingly, it has been reported that CRC cell lines are more resistant to ferroptosis induced by erastin (SLC7A11 inhibitor) than other cancer cells." (PMID 39079386, 2024). "Similarly, another study reported that CD8+ T cell-secreted IFN-γ suppresses SLC7A11, promoting cancer cell ferroptosis and thereby sensitizing cancer cells to radiotherapy." (PMID 39614322, 2024). "The role of SLC7A11 expression has been reported in several cancers." (PMID 39335604, 2024). "This underscores the potential of SLC7A11 as a druggable target and emphasizes the importance of further exploration into the development of precision therapies aimed at disrupting the metabolic dependencies of cancer cells." (PMID 38655266, 2024). "The transcriptional regulation of SLC7A11 is highly compatible with the mechanism of action of HMGA1, suggesting that HMGA1 may regulate SLC7A11 at the transcriptional level to achieve cancer cells’ resistance to ferroptosis." (PMID 38383528, 2024). "Additionally, the discovery of disulfidptosis highlights the metabolic vulnerability of SLC7A11 overexpressing cancer cells, offering new insights into cancer treatment by targeting their dependency on glucose and NADPH." (PMID 39687628, 2024). "For example, targeting specific components of the chromatin remodeling machinery involved in SLC7A11 transcription may enhance the efficacy of treatments designed to modulate oxidative stress in cancer cells." (PMID 39532848, 2024). "Thus, in cancers marked by a high expression of SLC7A11, disulfidptosis presents a therapeutic opportunity to control cancer progression via pharmacological or genetic interventions." (PMID 38739940, 2024). "Then, qRT-PCR was subsequently employed to compare the mRNA transcript levels of SLC7A11 in three cancer cell lines and their normal counterparts, including the 786-0 cell line, the HK-2 cell line, the SNU449 cell line, the LO2 cell line, the U20S cell line, and the hFOB1.19 cell line." (PMID 38397869, 2024). "Inhibition of glucose transporters to induce disulfidoptosis may be an effective therapeutic strategy for treating SLC7A11 high tumors, which frequently occur in human cancers." (PMID 38862242, 2024). "Given that high SLC7A11 expression is a key feature of certain cancers, these findings indicate that disulfidptosis could serve as the basis of innovative anti-cancer therapies." (PMID 38739940, 2024). "According to this, SLC7A11 is highly expressed in most cancers, including CRC, and its overexpression is closely associated with oxidative stress block, chemoresistance and poor outcome of cancer patients." (PMID 39061826, 2024). "However, the adaptive upregulation of SLC7A11 and GPX4 hinders radiotherapy efficacy; hence, inactivating SLC7A11 or GPX4 with ferroptosis inducers yields radioresistant cancer cells and xenograft tumors." (PMID 38844964, 2024). "Another study found a correlation between SLC7A11 expression and cancer prognosis." (PMID 39335604, 2024). "This discrepancy may be explained by the adaptation of cancer cells with low SLC7A11 expression to reduced GSH levels in vivo." (PMID 39353906, 2024). "Thus, targeting the SNF2L/SLC7A11 axis holds promise for advancing personalized cancer therapies, particularly in subtypes with low SNF2L expression and high oxidative stress." (PMID 39532848, 2024). "Furthermore, our pan-cancer analysis unveiled a close association between SLC7A11 expression, PD-L1 expression, and poor overall survival across multiple cancer types, indicating the broader implications of SLC7A11 and ferroptosis in cancer beyond LUAD." (PMID 38655266, 2024).
cancer (continued). "The aberrant regulation of key factors involved in ferroptosis and their regulators is closely linked to cancer progression, and targeting the ferroptosis network, particularly GPX4 and SLC7A11, may offer new therapeutic options for cancer and other diseases." (PMID 39771583, 2024). "IFN-γ secretion decreases SLC7A11 expression, suggesting that combining SLC7A11 inhibitors with immunotherapy could improve cancer treatment." (PMID 39040097, 2024). "Moreover, SLC7A11 is often overexpressed in tumors, and cancer cells depend on SLC7A11-mediated cystine uptake to regulate redox homeostasis and promote cell survival." (PMID 38182642, 2024). "FINs targeting SLC7A11 can enhance the sensitivity of cancer cells to chemotherapy drugs." (PMID 39769177, 2024). "Moreover, this study highlights that using inhibitors of glucose transporters induces disulfidptosis in cancer cells with high SLC7A11 expression, effectively suppressing the growth of SLC7A11-overexpressing tumors." (PMID 38319721, 2024). "Since NRF2 and SLC7A11 are vital for cellular antioxidant responses and often dysregulated in cancers, understanding the precise role of SNF2L could identify novel therapeutic targets." (PMID 39532848, 2024). "Our study indicates that gaining a deeper understanding of the functions of cysteine and SLC7A11 in controlling the redox activity proteins and their interactions could present a promising strategy for treating cancer." (PMID 39807126, 2024). "SLC7A11 plays a key role in ferroptosis and cancer development." (PMID 39437660, 2024). "Ever since Bannai and Kitamura first identified it in 1980, there has been a significant rise in the number of studies showing the extensive presence of SLC7A11 in different types of cancer, along with its various impacts on cancer development, spread, migration, and poor prognosis." (PMID 39807126, 2024). "On the other hand, activated SLC7A11 enhances cystine uptake to facilitate cancer cell growth." (PMID 40440083, 2024). "Interestingly, it was recently reported that SLC7A11 drastically increases the expression of c-Myc through cysteine in cancer stem cells." (PMID 38862581, 2024). "Indeed, USP18 knockdown significantly reduced SLC7A11 levels in multiple human cancer lines, but had moderate effects on SLC7A11 mRNA levels." (PMID 38959043, 2024). "SLC7A11 acts as a link between cancer metabolic disorders and ferroptosis." (PMID 38605214, 2024). "Several miRNAs also regulate post-transcriptionally SLC7A11 levels, which is post-translationally stabilized by an interaction with CD44v9 (a variant of the CD44 stemness marker of several cancers) leading to inhibition of proteosomal degradation in cancer." (PMID 37132605, 2024). "For example, genetic ablation or pharmacological inhibition of SLC7A11 strongly induces ferroptosis in various cancer cell types, whereas SLC7A11 overexpression in cancer cells promotes glutathione biosynthesis, confers ferroptosis resistance, and is associated with unfavorable patient outcomes." (PMID 39420439, 2024). "In addition, accumulating evidence suggests that SLC7A11 promotes cancer progression in part by inhibiting ferroptosis, a form of programmed cell death caused by excessive lipid peroxidation." (PMID 37210575, 2023). "Consistent with this, cisplatin-sensitive BC cell lines and patient-derived organoids exposed to cisplatin for as little as 48 h exhibited similar mechanisms of SLC7A11 upregulation and chemoresistance, trends that were also reflected in public cancer survival databases." (PMID 38023731, 2023). "In many cancers, high expression of SLC7A11 is indicative of a poorer prognosis." (PMID 38132439, 2023). "Also, the crucial role played by glutamate in the maintenance of redox homeostasis by exchanging extracellular cystine in exchange for intracellular glutamate through the cystine-glutamate transporter (xCT/SLC7A11) was investigated in cancer." (PMID 36817470, 2023).
cancer (continued). "In this study, we showed that, whereas moderate overexpression of SLC7A11 protects cancer cells from H2O2-induced cell death, counterintuitively, high overexpression of SLC7A11 potently induces cell death under H2O2 treatment by depleting NADPH and inducing disulfide stress." (PMID 37339981, 2023). "SLC7A11 has been shown to promote cancer progression by inhibiting ferroptosis in recent studies." (PMID 37210575, 2023). "Notably, NDUFA11, OXSM, LRPPRC, NCKAP1, RPN1, SLC3A2, and SLC7A11 were upregulated in cancer tissues, while NDUFS1 showed the opposite trend." (PMID 38213838, 2023). "In cancer cells, inhibition of system SLC7A11-mediated cystine uptake by ERA may be sufficient to initiate ferroptosis by interfering with GSH and GSSG intracellular levels." (PMID 37260977, 2023). "In turn, SLC7A11, a cystine/glutamate antiporter conferring specificity for cystine uptake, promotes the synthesis of reduced glutathione to limit oxidative damage and protect cancer cells from apoptosis." (PMID 37612452, 2023). "Glucose starvation induced apoptosis in cancer cells with relatively high SLC7A11 expression level." (PMID 37315289, 2023). "SLC7A11 has been observed to express in various cancer tissues and plays different functions in a number of pathophysiological processes, including ferroptosis, immune system function, metabolic flexibility/nutrient dependency and redox homeostasis (Jyotsana, Ta & DelGiorno, 2022)." (PMID 36874967, 2023). "Therefore, we conducted this systematic review and meta-analysis to identify the prognostic and clinicopathological significance of SLC7A11 in human cancers." (PMID 36874967, 2023). "Correlations between SLC7A11 gene expression and the potency of 1400 anticancer agents over 60 human cancer cell lines revealed 12 as inhibitor and substrate of system Xc− with half maximal inhibitory concentration (IC50) values ranging from 0.86 to 53 μM in different carcinoma cell lines." (PMID 36658724, 2023). "Inactivation of SLC7A11 induces ferroptosis in a variety of cancer cells." (PMID 37266741, 2023). "Notably, overexpression of the cystine-glutamate transporter SLC7A11 has been observed in various human cancers." (PMID 38105650, 2023). "SLC7A11 overexpression promotes cancer progression by suppressing ferroptosis." (PMID 37807410, 2023). "TC-11 even exported glutamate, a mechanism, which might increase cancer cell dependency on glucose via the glutamate/cystine antiporter SLC7A11." (PMID 36834608, 2023). "A transport protein of xC−, SLC7A11, is overexpressed in many cancers." (PMID 38203246, 2023). "Taking these results together, we could infer that SLC7A11 is a potential oncogene in human cancers." (PMID 36874967, 2023). "Finally, our results suggest that ferroptosis is induced in both NAT10-depleted and Remodelin-treated cancer cells at different stages of the SLC7A11/GSH/PLOOH axis." (PMID 37237981, 2023). "Mechanistically, high cystine uptake in cancer cells with high overexpression of SLC7A11 in combination with H2O2 treatment results in toxic buildup of intracellular cystine and other disulfide molecules, NADPH depletion, redox system collapse, and rapid cell death (likely disulfidptosis)." (PMID 37339981, 2023). "SLC7A11 has been confirmed to be overexpressed in some kinds of cancer and attenuate ferroptosis." (PMID 37552314, 2023). "Therefore, SLC7A11 is regarded as a promising target in therapy for different cancers, including EC." (PMID 37564206, 2023). "SLC7A11 plays a crucial role in mediating disulfidptosis, a unique form of cell death characterized by the accumulation of intracellular disulfide molecules in cancer cells with dysregulated expression of the cystine transporter." (PMID 37427103, 2023).
cancer (continued). "Many cancer cells may be effectively induced to undergo ferroptosis by eliminating cystine or preventing SLC7A11 from functioning via gene ablation or pharmacological suppression." (PMID 37576601, 2023). "This way, SLC7A11 overexpression makes cancer cells addicted to glutamine and glucose." (PMID 38203246, 2023). "To test this hypothesis, we analyzed SLC7A11 expression and cystine uptake levels across a panel of cancer cell lines." (PMID 37339981, 2023). "Although the exact implication of disulfidptosis activity on cancer patients’ immune characteristics is still unknown, two disulfidptosis-related gene SLC7A11 and SLC3A2, has been reported to play a role in the immune process during tumorigenesis." (PMID 37587262, 2023). "Further understanding this context-dependent function of SLC7A11 in cancer might provide important insights into therapeutic targeting of the disulfide stress–induced metabolic vulnerability in certain SLC7A11-high cancers." (PMID 37339981, 2023). "Due to the role played by GSH in regulating redox balance, some molecules involved in GSH metabolism, such as glutathione peroxidase 4 (GPX4), GCLC and the cystine transporter solute carrier family 7 member 11 (SLC7A11), have been reported to inhibit the ferroptosis of cancer cells." (PMID 37443154, 2023). "Moreover, the inhibition of SLC7A11 or GPX4 has been shown to enhance IR sensitivity in radioresistant cancer cells and xenografts." (PMID 37488128, 2023). "Histopathologic analyses showed that liver specimens from the mice injected with SLC7A11-low or -moderate cancer cells frequently harbored large metastatic nodules, whereas those injected with SLC7A11-high cancer cells occasionally contained small metastatic nodules." (PMID 37339981, 2023). "When converted to cysteine, xCT (also known as SLC7A11) acts as a precursor for GSH biosynthesis, and increased xCT expression is associated with chemoresistance and nutrient dependence in a variety of cancers." (PMID 36929586, 2023). "The OTUB1 can mediate ferroptosis via the stabilization of SLC7A11 in human cancer." (PMID 37714846, 2023). "Erastin, a RAS-selective lethal small molecule, could induce cancer cell ferroptosis by inhibiting the activity of SLC7A11." (PMID 36926345, 2023). "Remarkably, such an anti-proliferative effect was significantly enhanced by ERA since the proliferation reduction reached 92% and 95% at 72 h in combined treatments, suggesting that SLC7A11 antiporter activity is necessary for cancer survival under HBP inhibition." (PMID 37260977, 2023). "As well, it has been shown that SLC7A11 may contribute to cancer progression in part by inhibiting ferroptosis, an excessive lipid peroxidation-induced form of programmed cell death." (PMID 37210575, 2023). "SLC7A11 has significant translational value in cancer treatment." (PMID 37880315, 2023). "Under glucose starvation, disulfidptosis is observed in cancer cells, where SLC7A11 expresses abnormally, cystine uptake increases, cystine reduces to cysteine, and the NADPH pool depletes, which results in excess accumulation of intracellular disulfide molecules and rapid cell death." (PMID 37250891, 2023). "In the cellular ferroptosis defense mechanism, GPX4 and SLC7A11 indeed play important roles, especially in malignant tumors where aberrant expression or function of GPX4 and SLC7A11 often accompanies and affects the susceptibility of cancer cells to ferroptosis." (PMID 37723588, 2023). "Therefore, SLC7A11 indirectly counteracts the polyunsaturated fatty acids oxidation enhancing the resistance to ferroptosis induced by anti-cancer drugs." (PMID 37397501, 2023). "SLC7A11 expression was significant high in 18 kinds of human cancers." (PMID 36874967, 2023).